FBXW7 (F-box and WD repeat domain containing 7)
Diseases named in the same sentence as FBXW7 in open-access papers (continued):
Sharing a sentence is not in itself a finding about the gene and the disease.
tumor (continued). "In conclusion, the present study demonstrated that APS treatment reduced the expression of miR-27a, and in turn results in the up-regulation of the tumor suppressive gene, FBXW7, finally leading to the reduction in cellular proliferation and the induction of apoptosis in OC." (PMID 32159214, 2020). "STYX and FBXW7 expression were measured both in EC tumor and normal tissues." (PMID 32239181, 2020). "FBXW7 is a critical tumor suppressor involved in the ubiquitin-proteasome system in human cancer." (PMID 33194745, 2020). "In summary, our work demonstrates that FBXW7 mediates c-Myc K48-linked ubiquitination to limit the accumulation of c-Myc, leading to the inhibition of M2-like TAM polarization, thereby exerting a tumor-suppressive effect." (PMID 33260160, 2020). "However, the role of FBXW7 in tumor immune microenvironment, particularly in TAM polarization, has not yet been described." (PMID 33260160, 2020). "FBXW7-knockout in mouse embryonic fibroblasts decreased E-cadherin expression and induced the occurrence of epithelial-to-mesenchymal transition, which promotes tumor metastasis." (PMID 33260160, 2020). "Considered that the same molecule or its isoforms may play a different regulatory role in macrophage activation states, several isoforms of FBXW7 may play different regulatory roles during macrophage differentiation and tumor progression." (PMID 33260160, 2020). "Several studies have attested that FBXW7 plays tumor suppressor roles in human cancer." (PMID 32239181, 2020). "And FBXW7 acts as a general tumor suppressor in many cancers." (PMID 32239181, 2020). "FBXW7 has been well characterised as a tumour suppressor in carcinogenesis and progression." (PMID 32655893, 2020). "FBXW7 plays a pivotal role in cell growth suppression and tumor inhibition." (PMID 32792479, 2020). "F-box/WD repeat-containing protein 7, FBXW7, mediator complex subunit 12 (MED12), and spen family transcriptional repressor (SPEN), three tumor suppressors associated with the regulation of the NOTCH1 pathway, were also identified as being mutated with low frequency in CLL." (PMID 32182763, 2020). "APS was identified to dose-dependently increase FBXW7 expression, and it was hypothesized that APS exerts its anti-tumor effects by enhancing FBXW7 expression." (PMID 32159214, 2020). "This may explain why FBXW7 functions as a tumor suppressor, while our data revealed that FBXW4 has oncogenic effects in AML." (PMID 32175272, 2020). "Finally, it was also observed that knockdown of FBXW7 by si-FBXW7 reversed the tumor suppressive activity of APS in OC cells, which is similar to the effects of miR-27a overexpression." (PMID 32159214, 2020). "Therefore, it suggests that FBXW7-knockout promotes pro-tumoral factors production in M2 macrophages and aggravates tumor progression upon M2 polarization." (PMID 33260160, 2020). "Targeting the MYC/NSD3S PPI interface may prove beneficial for patients with MYC amplification, as their disruption may restore the binding between MYC and the tumor suppressor FBXW7." (PMID 31638140, 2020). "Impaired NOTCH1 activity may result in the activation of specific oncogenes (c-MYC, NFkB, or mTOR) or inhibition of tumor suppressor expression (FBXW7, PTEN, CDKN1B)." (PMID 32766158, 2020). "However, little is known about the functions of FBXW7 in macrophages and the tumor immune microenvironment." (PMID 33260160, 2020). "Fbxw7 has been previously found responsible for the ubiquitylation and subsequent degradation of a set of oncoproteins such as cyclin E, c-Jun and c-Myc via K48 linkage, which earned Fbxw7 recognition as a tumor suppressor." (PMID 31632280, 2019). "Besides, miR-92a probably acts as a driver of tumor progression through targeting FBXW7, which highlighting the potential functions of miR-92a on prognosis and treatment of OS." (PMID 30804710, 2019). "Thus, enhancing the tumor suppressive activity of FBXW7 through its regulators can serve as a novel approach in cancer." (PMID 30791487, 2019).
tumor (continued). "Studies have found downregulation of FBXW7 in HCC tissues compared to their adjacent tumor tissues, which may contribute to increased tumor size, and poor prognosis." (PMID 30791487, 2019). "So far, studies of Fbxw7 have been mainly focused on its tumor suppression." (PMID 31371703, 2019). "Interestingly, 32 of the 130 predicted SLIs occurred with FBXW7, a well-known tumor suppressor that functions as a substrate-recognition protein within a SKP/CUL1/F-Box ubiquitin ligase complex for proteasome degradation." (PMID 31351478, 2019). "Fbxw7 is a tumor suppressor that acts via regulation of cell growth, division, and differentiation." (PMID 31371703, 2019). "These experiments are consistent with a study performed in cancer cell lines, which shows that the substrate recognition component of SCF, F-box and WD repeat domain-containing 7 (Fbw7), elicits its tumor suppressive function by targeting Med13 and Med13L for degradation." (PMID 30621145, 2019). "Furthermore, immunohistochemical staining suggested that the expression of TRIP13, Ki67 and c-MYC was significantly reduced in TRIP13-knockdown tumours compared with controls, while the expression of FBXW7 was increased." (PMID 31740732, 2019). "It is clear that FBXW7 (F-box and WD repeat domain-containing 7) plays the role of tumor suppressor, being involved in ubiquitination and degradation of several oncoproteins, such as c-Myc, Cyclin E, Notch, SREBP (sterol regulatory element-binding protein), Mcl1 and many others." (PMID 31569395, 2019). "Our results revealed that circ-FBXW7 plays a tumor suppressor role in CRC." (PMID 31519156, 2019). "Furthermore, the mechanisms relating to how FBXW7 executes its role as a tumor suppressor to enhance chemosensitivity in NSCLC are poorly elucidated." (PMID 29633504, 2018). "We observed a statistically significant increase in the number of lung tumors in Fbxw7+/− mice in agreement with the hypothesis that this gene is a general tumor suppressor in multiple tissues." (PMID 29633504, 2018). "On the other hand, FBXW7 is a tumor suppressor and its inactivation could result in the constitutive activation of NOTCH1, cyclin E, c-Myc and other oncogenic factors." (PMID 29506494, 2018). "FBXW7 is an essential tumor suppressor and is frequently inactivated in human cancer cells." (PMID 30086763, 2018). "Hence, KSHV-infected tumor cells increase cell proliferation by reducing FBXW7-mediated Notch degradation." (PMID 30086763, 2018). "In addition, it is reported that the expression of FBXW7 mRNA is reduced in paired tumor and non-tumor tissues in gastric adenocarcinoma patients." (PMID 30086763, 2018). "The role of FBXW7 as a tumor suppressor is well established." (PMID 30086763, 2018). "Aberrant FBXW7 mRNA expression is correlated with lymph node metastasis and tumor stage III-IV." (PMID 30086763, 2018). "FBXW7, known as a general tumor suppressor, is commonly lowly expressed in metastatic malignancies." (PMID 29097832, 2017). "Up-regulated in serum and tissues of ESCC patients, miR-223-3p could inhibit tumour-suppressor gene F-box and WD repeat domain-containing 7 (FBXW7) and demonstrate a poor prognosis." (PMID 28380431, 2017). "This patient's tumor demonstrated 8 mutations overall including alterations in the PI3K, MAPK pathways (mutations in FBXW7, FGFR1) with concurrent epigenetic and transcriptional deregulation, specifically ARID1A, ETV1 rearrangement, NOTCH1 APIP-NOTCH1 fusion, and MYST3 amplification." (PMID 28781987, 2017). "FBXW7 is widely considered to be an effective tumor suppressor gene." (PMID 28464881, 2017).
tumor (continued). "Additionally, FBXW7 expression at the cancer invasion front was lower than that in the center of the primary tumor." (PMID 29348852, 2017). "It has been shown that down regulation of FBXW7 can promote tumor cell proliferation." (PMID 28464881, 2017). "In our previous studies, FBXW7 has been confirmed to be an tumor suppressor in HCC." (PMID 28716020, 2017). "Generally, FBXW7 is regarded as a tumor suppressor in a variety of human cancers." (PMID 29097832, 2017). "Recent studies have demonstrated that FBXW7 is a tumor suppressor." (PMID 28149200, 2017). "Moreover, previous studies suggested that FBXW7 suppressed EMT of tumor cells by targeting c-Myc, Notch, mTOR and RhoA signaling pathway." (PMID 28716020, 2017). "Additionally, Fbxw7, Pdcd4, and Stk40 (tumor-suppressor targets of miR-223, -21, and -31) were downregulated in marked-ZD cohort." (PMID 26918602, 2016). "Thus, upregulation of oncogenic miR-223, -31, and -21 is accompanied by down-regulation of their respective tumor suppressor target Fbxw7, Stk40 and Pdcd4." (PMID 26918602, 2016). "Generally, FBXW7 is regarded as a tumor suppressor in human cancers." (PMID 25749036, 2015). "Reduced FBXW7 protein level was also found in six of seven primary CCA tumors relative to adjacent nontumorous bile duct, implicating FBXW7 may also be a tumor suppressor in CCA as reported in other types of tumors." (PMID 25749036, 2015). "FBXW7, also known as F-box and WD repeat domain-containing 7, has been found to be involved in numerous cellular processes including cell proliferation, apoptosis, cell cycle, differentiation and its expression change is related to tumor prognosis." (PMID 25888377, 2015). "How does the decrease in FBXW7 function result in tumor development?" (PMID 26575021, 2015). "Since most of its substrates are growth-promoting, Fbxw7 is thought of as a tumor suppressor." (PMID 26634163, 2015). "FBXW7 is regarded as a general tumor suppressor in human cancer." (PMID 25749036, 2015). "Moreover, although the role of FBXW7 as a tumor suppressor is well documented in hematopoietic tumors in which mutations in FBXW7 are unequivocally linked to tumorigenesis, this is not as clear for other cancer types." (PMID 25669969, 2015). "We propose that FBXW7 can also act as a tumor maintenance gene in the context of MYC deregulation." (PMID 25669969, 2015). "Fbxw7 is a key tumor suppressor that regulates cell proliferation in different HCC cell lines." (PMID 26617467, 2015). "Fbxw7 acted as a tumor suppressor by promoting both apoptosis and growth arrest in HCC." (PMID 24884509, 2014). "We thus sought to determine whether Fbxw7 acted as a tumor suppressor in HCC in a similar fashion, i.e. by promoting apoptosis and inhibiting cell proliferation." (PMID 24884509, 2014). "We initially investigated the expression of the Fbxw7 protein in 60 HCC patients using immunohistochemistry and western blotting, and our data showed that the expression of Fbxw7 was significantly lower in HCC compared with matched normal tumor-adjacent tissues." (PMID 24884509, 2014). "Our previous study showed that Fbxw7 functions as a tumor suppressor and that it may be involved in apoptosis and proliferation in HCC." (PMID 24884509, 2014). "We next sought to determine whether Fbxw7 affects tumor growth by inhibiting YAP using a Hep3B subcutaneous tumor model." (PMID 24884509, 2014). "Interestingly, we observed EGF-induced alternative promoter usage of genes that have previously been implicated in tumor progression (e.g., VEGFC, PTK2, IL18 and VAV3) or in cell survival/proliferation (e.g., FBXW7, BID, ABL2)." (PMID 24324612, 2013).
tumor (continued). "Based on the known tumor suppressor function of FBXW7 and the previous report of an RCC associated constitutional translocation that disrupts FBXW7, we suspect that UBE2QL1 inactivation compromises FBXW7 function although further studies are required to elucidate the exact mechanism." (PMID 24000165, 2013). "FBXW7 acts as a tumor suppressor through ubiquitination and degradation of multiple oncoproteins." (PMID 23166673, 2012). "F-box and WD repeat domain-containing 7 (FBXW7) is a cell cycle regulatory gene whose protein product ubiquitinates positive cell cycle regulators such as c-Myc, cyclin E, and c-Jun, thereby acting as a tumour-suppressor gene." (PMID 22108521, 2012). "Studies in mice additionally support a tumor suppressive activity of Fbxw7/hCdc4." (PMID 21122106, 2010). "Tumor specimens were classified as low or high methylation (see Materials and methods for details on quantification and classification of promoter methylation), divided into two groups and compared with the mRNA expression levels of FBXW7/hCDC4-β." (PMID 21122106, 2010). "FBXW7 serves as a negative regulator of oncoprotein and is a general tumor suppressor." (PMID 21114830, 2010). "Given the number of its targets and the fact that FBXW7 is translated into three different isoforms with distinct subcellular localization, possible mechanisms of tumor suppression are bound to be complex and variable depending upon the cell type in which downregulation occurs." (PMID 17326833, 2007). "In addition, levels of FBXW7 were correlated with survival indicating a possible implication in tumor aggressiveness." (PMID 17326833, 2007). "However, many important FBXW7 targets involved in tumor development remain to be characterized." (PMID 40083925, 2025). "Notably, FBXW7 is a critical tumor suppressor of human cancers." (PMID 40169588, 2025). "In the meantime, in vitro investigations revealed that FBXW7 may serve as a tumor suppressor gene in CRC, inhibiting proliferation and metastasis of CRC cells via two different mechanisms: reduction in arginine production through metabolic reprogramming and direct down-regulation of mToR signaling." (PMID 39823500, 2025). "These intrinsic events within tumor cells enhance ER stress‐associated ubiquitylation and degradation by triggering ubiquitin via the E1 activase UBA6, facilitating ubiquitin transferring to E2 conjugate UBE2Z and increasing the activities of E3 ligase FBXW7 to degrade both EZH2 and MYC." (PMID 39823459, 2025). "Synthetic lethal approaches being investigated in tumor-agnostic studies include PARP inhibitors for BRCA1/2- or ATM-mutant cancers; ATR inhibitors for ATM-mutant cancers; and PKMYT1 inhibition for solid tumors with CCNE1 amplification, FBXW7 loss, and PPP2R1A mutations (NCT04855656)." (PMID 38938274, 2024). "The absence of FBXW7 could serve as an independent prognostic marker and was found to be significantly associated with tumor cell resistance to chemotherapeutic agents and poor disease prognosis." (PMID 36860568, 2023). "Considering the combined findings of two genes involved in tumor clusterization, FBXW7 and SREBF1, it is hypothesized that these tumors exchange autophagy-related processes and large-scale technologies based on their aggressiveness and treatment sensitivity or resistance." (PMID 37628602, 2023).
tumor (continued). "Thus, FBXW7 may be involved in tumor cell evasion of the apoptotic program and the consequent generation of therapy resistance by regulating the ubiquitination and hydrolysis of anti-apoptotic factors." (PMID 38027013, 2023). "In addition to its tumour suppressor function, FBXW7 also facilitates development of the cardiovascular system, a feature most notably displayed in FBXW7 knockout animals which present with major vascular impairment due, in part, to unrestrained NOTCH activation." (PMID 37183425, 2023). "FBXW7 also influences macrophages, as its deficiency leads to improved expression of chemokine C-C Motif Chemokine Ligand 2 (CCL2) in serum, resulting in the recruitment of macrophages and monocytic myeloid-derived cells and eventually resulting in tumor metastasis." (PMID 36998461, 2023). "Moreover, FBXW7 may also be involved in other mechanisms of tumor resistance development (e.g., enhanced DNA repair, drug target alteration, epigenetic alteration, promotion of drug metabolism and detoxification)." (PMID 38027013, 2023). "Thus, regulation of FBXW7 stability is crucially involved in tumor development." (PMID 36934104, 2023). "Interestingly, recent data concerning biomolecular characteristics of GS documented that, although GS has a genetic profile that overlaps with GBM and other neoplasms, it is also true that GS has its genetic mutations, such as MSH6, BRAF, SUZ12, SOX2, and FBXW7." (PMID 38202090, 2023). "Interestingly, USP28 counteracts the activity of the F-box and WD repeat domain containing protein 7 (FBXW7), a tumour suppressor protein that is part of the SCF (Skp1, Cullin-1, F-box) protein complex and facilitates the ubiquitination and destabilisation of MYC among other proteins." (PMID 37202505, 2023). "However, miR-182 was found to increase tumor progression by targeting FBXW7." (PMID 37438760, 2023). "Interestingly, FBXW7 plays a crucial role in maintaining stem cells in various tissues, including cancer stem cells (CSCs), which are a small subset of tumor cells with the ability to initiate tumors, and promote tumor spread, recurrence, and chemoresistance." (PMID 37408248, 2023). "Therefore, FBXW7 has been designated as a well-established tumor suppressor." (PMID 36104351, 2022). "This research found that binding of PLK2 to the tumor suppressor Fbxw7 resulted in increased degradation of Fbxw7 and stabilization of Cyclin E; this suggested that PLK2 may act as a tumor supportive factor, may serve as a prognostic and diagnostic target and furthermore as a therapeutic target." (PMID 35053604, 2022). "Circ-FBXW7, highly expressed in normal human brain, has been reported to encode a novel 21-kDa protein, named FBXW7-185aa, that reduces the half-life of c-Myc by antagonizing USP28-induced c-Myc stabilization, thus acting as tumor suppressor in glioblastoma cells." (PMID 36338714, 2022). "In B-lymphoma cells, the mutation or knockdown of CREBBP or EP300 inhibited H3K27 acetylation, downregulated FBXW7 expression, activated the NOTCH pathway, and downstream CCL2/CSF1 expression, resulting in tumor-associated macrophage polarization to M2 phenotype and tumor cell proliferation." (PMID 33431788, 2021). "Therefore, the miR‐223/FBXW7/NOTCH axis may outline a promising therapeutic target for NSCLC patients whose neoplasms are resistant to erlotinib." (PMID 33822486, 2021).